ATOH1 (atonal bHLH transcription factor 1)
Diseases named in the same sentence as ATOH1 in open-access papers (continued):
Sharing a sentence is not in itself a finding about the gene and the disease.
deafness (11 papers, 2012 to 2025). An inherited or acquired condition characterized by the complete loss of the ability to hear from one or both ears. "Pou4f3, a Pou family transcription factor, is the dominant nonsyndromic deafness 15 (DFNA15) deafness-causative gene and a downstream target of Atoh1 activation." (PMID 37207182, 2023). "Atoh1 overexpression induces new hair cells, and triggering the differentiation of new hair cells is a potentially useful approach to the treatment of deafness caused by hair cell loss." (PMID 39883720, 2025). "With the Pou4F3DTR deafness model we can now continue to investigate Atoh1-induced regeneration in mature mammals and explore means to enhance it." (PMID 33293609, 2020). "One possible explanation for this contrasting result is the differences in the severity of deafness and therefore the extent OC degeneration prior to ATOH1 introduction." (PMID 25036727, 2014). "Moreover, the inclusion among the DEGs of genes involved in inner ear development and deafness (Atoh1, Edn1, Hes1, Kl, Myc, Mycn and Olig1) suggested their interaction with Dmp1 in these processes." (PMID 37106825, 2023). "In a guinea pig model of deafness generated by ototoxic drug-induced HC death, Atoh1 was injected into the cochlea of deaf animals via an adenoviral vector to increase its expression in nonsensory cells, showing that new HCs were produced at the original site of cochlear trauma." (PMID 37207182, 2023). "Thus, Tbx2 is essential for IHC development and co-upregulation of Tbx2 with Atoh1 in supporting cells represents a new approach for treating deafness related to IHC degeneration." (PMID 36687561, 2022). "Furthermore, interestingly enough, supporting cells can be converted into hair cells by upregulating Atoh1 expression, which provides another approach attempted for deafness gene therapy." (PMID 31096644, 2019). "When combined with other treatments such as manipulation of the Notch signalling pathway to decrease inhibitory signalling or after forms of deafness that result in less severe damage to the OC, ATOH1 gene therapy may lead to functional improvement." (PMID 25036727, 2014). "The current work found a series of DEGs related to sensory epithelial development and cytoskeleton organization through functional enrichment and PPI network analysis, including ATOH1, VIM, PRPH and NEFL, which may be involved in the pathogenesis of ELMOD3 causing deafness." (PMID 37708136, 2023). "This study contributes a novel genetic mechanism that Atoh1 functions as a transcriptional activator of Barhl1 through the E3 box to achieve regulation of hair cell development, which can help us to better understand the pathogenesis of deafness and find relevant cues." (PMID 31096644, 2019). "In contrast, in a model of aminoglycoside-induced profound deafness, although Atoh1 gene therapy induced the conversion of nonsensory cells in the cochlea into HCs, the resulting HCs failed to mature fully and did not improve hearing in the treated animals." (PMID 37207182, 2023). "Our current Atoh1-cre Atoh1 CKO mice can live into adulthood without any gross phenotypes beyond deafness and some vestibular dysfunction." (PMID 22279587, 2012). "Furthermore, the percentage of HCs that had CtBP2 puncta after ATOH1 treatment was not different to those examined after four days of deafness." (PMID 25036727, 2014). "Collectively, these data suggest that, whilst ATOH1 alone can drive non-sensory cells towards an immature sensory hair cell phenotype in the mature cochlea, this does not result in functional improvements after aminoglycoside-induced deafness." (PMID 25036727, 2014).
hearing loss (11 papers, 2012 to 2025). "Expression of Atoh1 has been found to be sufficient to drive auditory hair cell differentiation, prompting several clinical trials of Atoh1 gene therapy for hearing loss." (PMID 39833721, 2025). "Many types of research have focused on Atoh1 for regenerating hair cells and improving this method as one option for sensory neural hearing loss, including ARHL." (PMID 38333758, 2024). "Reprogramming of the cochlea with hair-cell-specific transcription factors such as ATOH1 has been proposed as a potential therapeutic strategy for hearing loss." (PMID 36445327, 2022). "Together, our studies represent a major step towards understanding cochlear HC regeneration in vivo, with the potential to further improve the ongoing ATOH1 gene therapy in the clinic for patients with hearing loss." (PMID 30063705, 2018). "Atoh1-based gene therapy, therefore, has the potential to treat noise-induced hearing loss if the treatment is carried out before hair cells die." (PMID 23029493, 2012). "This could also have implications for the design of gene-therapeutic trials to reverse human hearing loss, which currently concentrate on key developmental genes - such as e.g. ATOH1." (PMID 32366993, 2020). "Given the projected massive occurrence of hearing loss in the next 25 years, ideas revolving around maintenance of HCs using Atoh1 alone might provide more-short term benefit compared to currently impossible reconstitution of the OC after long term HC loss." (PMID 25698932, 2015). "Moreover, using transient expression of Atoh1 in already differentiated HCs might prolong their viability, possibly long enough to sidestep the need for OC regeneration in elderly people suffering from early stages of neurosensory hearing loss." (PMID 25698932, 2015). "However, if Atoh1 treatment can stabilize injured hair cells and directly or indirectly promote repair, such treatment may be effective for treating both noise- and drug-induced hearing loss." (PMID 23029493, 2012). "Thus, Atoh1-based gene therapy may not be suitable for the treatment of all types of noise-induced hearing loss." (PMID 23029493, 2012). "Pre-clinical research on ATOH1 and OTOF are always conducted on animal models rather than model animals therefore the research findings will never reliably translate to clinical forms of hearing loss." (PMID 40003934, 2025).
colitis (9 papers, 2014 to 2024). Inflammation of the colon. "The secretory progenitor cells marked by the transcription factor Atoh1 have also been shown to repopulate the colonic epithelium during DSS-induced colitis." (PMID 32869114, 2020). "Also, the analysis showed that both Dll1+ve and Dll4+ve IECs that were found in the DSS-colitis mice maintain their expression of ATOH1." (PMID 24860699, 2014). "These Atoh1+ cells can also repair and replenish the colonic epithelium during DSS-induced colitis." (PMID 32869114, 2020).
gastric cancer (6 papers, 2011 to 2023). A primary or metastatic malignant neoplasm involving the stomach. "In the present study, we found that the induction of ATOH1 expression can reduce the proliferation, invasion, and tumorigenicity of gastric cancer cells." (PMID 25950549, 2015). "Our observations suggest the possibility that the ATOH1 gene should be viewed as potential treatment target for gastric cancer." (PMID 25950549, 2015). "Although the expressional statuses of ATOH1 have been reported in normal gastric mucosa and in gastric cancer, its roles are poorly characterized." (PMID 25950549, 2015). "In addition, the induction of ATOH1 in gastric cancer cell lines and in GCSCs significantly reduced their tumorigenicity in subcutaneous injection and liver metastasis models." (PMID 25950549, 2015). "Interestingly, the overexpression of ATOH1 significantly decreased the proliferations of various types of gastric cancer cell lines and sphere formation by GCSCs." (PMID 25950549, 2015). "Here we show that ATOH1 can induce the differentiation of gastric cancer stem cells (GCSCs)." (PMID 25950549, 2015). "To determine whether ATOH1 can regulate the in vivo tumorigenicity of gastric cancer cells, we used a liver metastasis model produced by injecting gastric cancer cells into the spleen (cells subsequently migrated to liver)." (PMID 25950549, 2015). "In particular, ATOH1 was found to induce the differentiation of gastric cancer stem cells, and thus, therapeutics targeting ATOH1 might be able to eradicate cancer stem cells." (PMID 25950549, 2015). "We found the transduction with ATOH1 increased the level of cleaved-caspase-3 and—caspase-9 in GCSCs and gastric cancer cell lines, suggesting that the intrinsic apoptosis pathway might be involved." (PMID 25950549, 2015). "Furthermore, the lentivirus-induced overexpression of ATOH1 in GCSCs and in gastric cancer cell lines significantly induced differentiation, reduced proliferation and sphere formation, and reduced in vivo tumor formation in the subcutaneous injection and liver metastasis xenograft models." (PMID 25950549, 2015). "After the RASSF4 promoter, which was coupled with the lucifease gene, was stably introduced into the gastric cancer cell lines (NCI-N87 and SNU216 cells), we examined effects of ATOH1 on the activity of luciferase." (PMID 25950549, 2015). "Notably, the overexpression of ATOH1 significantly reduced tumor formation in liver by GCSCs and by NCI-N87 gastric cancer cells." (PMID 25950549, 2015).
Ataxia (5 papers, 2017 to 2026). Ataxia refers to impaired coordination of voluntary muscle movement. "Tox3-deficient mice display severe ataxia and cerebellar hypoplasia, driven by depletion of GNPs, diminished Atoh1 expression, and impaired primary cilia." (PMID 41849381, 2026). "Importantly, reduced cerebellar size correlated with behavioral deficits in Tg (Atoh1-Cre +);Brd4fl/fl mice, which exhibited symptoms of cerebellar ataxia not evident in Tg (Atoh1-Cre−);Brd4fl/fl mice." (PMID 31292434, 2019). "Thus, abnormal cerebellar function or ataxia does not explain the abnormal respiratory chemoresponses observed in Atoh1::En1-CKO mice." (PMID 29972353, 2018).
adenoma (3 papers, 2007 to 2019). A neoplasm arising from the epithelium. "Furthermore, ATOH1 mRNA levels are significantly lower in adenocarcinoma samples compared to adenomas (t-test: p = 0.017), indicating progressive loss of ATOH1 expression levels with increasing tumor severity." (PMID 19243219, 2009).
glioma (3 papers, 2021 to 2022). A benign or malignant brain and spinal cord tumor that arises from glial cells (astrocytes, oligodendrocytes, ependymal cells). "It has been confirmed that Atoh1 reduced the incidence of glioma and extended survival." (PMID 37786890, 2022). "The phosphorylation of KDM1A Ser683, PGK1 T243, Atoh1 tyrosine 78, YTHDF2 Ser39, and Thr381 can promote tumorigenesis, and if we can effectively control the phosphorylation of these proteins, we can prevent the development of glioma." (PMID 37786890, 2022).
Merkel cell carcinoma (3 papers, 2009 to 2025). "Here, we show that MCPyV+ Merkel cell carcinoma is defined by neuroendocrine-lineage core regulatory (CR) transcription factors (TFs) (ATOH1, INSM1, ISL1, LHX3, POU4F3, and SOX2) that were essential for tumor survival and that co-bound chromatin with the viral small T antigen at super enhancers." (PMID 41392987, 2025).
respiratory failure (3 papers, 2015 to 2018). The significant impairment of gas exchange within the lungs resulting in hypoxia, hypercarbia, or both, to the extent that organ tissue perfusion is severely compromised. "This study thus answers the decades-old question about the cause of respiratory failure in Atoh1-null mice: they die of an inability to modulate respiratory rhythms in response to hypoxic and hypercapnic conditions." (PMID 29972353, 2018). "Atoh1-null mice die at birth from respiratory failure, but the precise cause has remained elusive." (PMID 29972353, 2018). "For example, mice lacking the transcription factor Atonal homolog 1 (Atoh1) die at birth of respiratory failure even though they generate some respiratory movements." (PMID 29972353, 2018). "Atoh1 null mutants (hereafter Atoh1−/−) do not establish a proper respiratory rhythm and die at birth of respiratory failure, but the development of the RTN and CO2 chemosensitivity have not been examined in these mutants." (PMID 25866925, 2015).
brain tumor (2 papers, 2021). "Like many bHLH TFs, ATOH1 itself is rarely mutated in brain tumors; its expression levels, however, are reported to be dysregulated in a number of brain tumor subtypes." (PMID 34012965, 2021). "To address whether KIF20A might be similarly crucial for maintaining the proliferation of brain tumor-initiating cells, we crossed the Kif20afl/fl floxed mice with Atoh1-CreER; Ptcfl/fl mice to generate a strain of compound mice carrying the Atoh1-CreER; Ptcfl/fl; Kif20afl/fl alleles." (PMID 33976373, 2021). "Some of the most well-studied of these TFs in development and brain tumors are OLIG2, atonal bHLH transcription factor 1 (ATOH1) and Achaete-Scute family bHLH transcription factor 1 (ASCL1)." (PMID 34012965, 2021).
colorectal adenocarcinoma (2 papers, 2018 to 2021). The most common type of colorectal carcinoma. "The cell line LS174T, a human colorectal adenocarcinoma, was used to evaluate Notch-dependent expression of ATOH1." (PMID 34485296, 2021).
intestinal tumor (2 papers, 2009 to 2021). "Mice defective in the atonal homolog 1 (Atoh1) transcription factor which is required for intestinal secretory (goblet, Paneth, enteroendocrine) cell differentiation display increased intestinal tumor predisposition." (PMID 33557139, 2021). "To investigate whether Atoh1 plays a role in intestinal tumors, we analyzed the function of the mammalian ato homolog, Atoh1, in colon tumorigenesis." (PMID 19243219, 2009).
Anxiety (1 paper, 2023). Intense feelings of nervousness, tension, or panic often arise in response to interpersonal stresses. "The hippocampus and the cerebellum are both involved in anxiety behaviors, therefore the elevated anxiety observed only in the conditional p75Atoh1-Cre might be due to developmental defects in the hippocampus induced by the deletion of p75NTR after Atoh1 is expressed." (PMID 37305555, 2023).
apneic episodes (1 paper, 2023).
depression (1 paper, 2018). "Atoh1-deletion from the rRL does not affect survival, but causes apneas and respiratory depression during hypoxia, likely due to loss of projections to the preBötzinger Complex and RTN." (PMID 29972353, 2018).
Hypertension (1 paper, 2023). The presence of chronic increased pressure in the systemic arterial system. "The association with SSTR2, ASXL1, and ATOH1 may suggest potential novel mechanism in the pathogenesis of hypertension that needs to be to further elucidated." (PMID 37059828, 2023). "Thus, the SSTR2, ATOH1 and ASXL1 genes are all novel hypertension candidate genes." (PMID 37059828, 2023).
itch (1 paper, 2022). "Based on their location, we predict that PB neurons relaying itch also lie within the Atoh1 macropopulation." (PMID 35134251, 2022).
lung carcinoma (1 paper, 2012). "Accordingly, increased SPTBN1 expression (and over-representation of aTOH1/cTOH3 in controls over cases) could plausibly protect against lung cancer by increasing immune surveillance, given that we know that smoking suppresses the CD4/CD8 T cell ratio." (PMID 22384118, 2012). "Notably, only aTOH1 with OR of 0.5, was derived from parent cTOH3 (2p16.3–16.1) where both cTOH3 and aTOH1 are significantly under-represented in lung-cancer cases compared to controls (OR = 0.69 and 0.5, p = 0.001 and 0.005, respectively)." (PMID 22384118, 2012).
metastatic tumors (1 paper, 2009). "We therefore propose that ATOH1 acts as a key switch regulating the transformation of pre-oncogenic epithelia to neoplastic and metastatic tumors." (PMID 19243219, 2009). "We took advantage of several established MCC cell lines with either high ATOH1 expression (MCC1 and MCC6, derived from less aggressive tumors) or low ATOH1 expression (MCC13, MCC14.2, and MCC26, derived from highly aggressive metastatic tumors)." (PMID 19243219, 2009).
mucinous adenocarcinoma (1 paper, 2021). An invasive adenocarcinoma composed of malignant glandular cells which contain intracytoplasmic mucin. "Microarray analysis showed attainment of more malignant potential by ATOH1 protein stabilization, suggesting the mechanism by which MC are more malignant than non-mucinous adenocarcinoma." (PMID 34582650, 2021).
Mucinous Colorectal Adenocarcinoma (1 paper, 2023). "It was found that SCF/c-KIT signaling promotes the production of MUC2 and Mucinous Colorectal Adenocarcinoma (MCA) tumorigenesis by maintaining the expression of ATOH1." (PMID 38054820, 2023).
mucinous tumors (1 paper, 2021). "Conversely, presence of mucinous component in rectal adenocarcinomas was a highly significant factor correlating with ATOH1 fold change, where median ATOH1 expression level was significantly higher in rectal adenocarcinomas with mucinous components compared to non-mucinous tumors (p <0.001)." (PMID 34582650, 2021).
neuroendocrine carcinoma (1 paper, 2024). A malignant neuroendocrine neoplasm composed of cells containing secretory granules that stain positive for NSE and chromogranin. "ATOH1 is expressed in MCC, however there is mixed data regarding the specificity of this marker for excluding other non-MCC neuroendocrine carcinomas." (PMID 39136002, 2024).
otitis media (1 paper, 2012). Inflammation of the anatomical structures of the middle ear, which is most often caused by an infectious process. "Atoh1 and SPDEF could be the therapeutic targets for otitis media associated with mucous cell metaplasia which is frequently considered “intractable” in the clinical settings." (PMID 22518155, 2012). "However, the similarity of the middle ear epithelium to the pulmonary epithelium, Atoh1, the upstream gene of Spdef which is involved in several pulmonary diseases, may also have a role in the mucous cell metaplasia of otitis media." (PMID 22518155, 2012). "The effective blockage of the Atoh1, SPDEF, or GFI1 expression in the early phase of disease may be a new strategy for treating intractable otitis media." (PMID 22518155, 2012). "There is no report to discuss the involvement of Atoh1, GFI1, or Spdef in otitis media." (PMID 22518155, 2012).
rectal adenocarcinomas (1 paper, 2021). "Yet, both HES1 and ATOH1 expression levels were significantly correlated with presence of mucinous component in rectal adenocarcinomas." (PMID 34582650, 2021). "In the present study, HES1 and ATOH1 were inversely expressed in rectal adenocarcinomas with mucinous component." (PMID 34582650, 2021). "The current work studied gene expression of 3 CSCs related genes, namely LGR5, HES1, and ATOH1 in rectal adenocarcinomas among young Egyptian patients." (PMID 34582650, 2021). "Additionally, the molecular characterization of rectal adenocarcinomas with mucinous components revealed high ATOH1 expression levels, adding supplementary evidence to its critical effect on cellular differentiation." (PMID 34582650, 2021).
rectal cancer (1 paper, 2021). A primary or metastatic malignant neoplasm that affects the rectum. "The study aimed to delineate the gene expression profile of LGR5, HES1 and ATOH1 in young Egyptian rectal cancer (RC) patients and investigate the correlation between expression profiles and clinical outcome." (PMID 34582650, 2021).